AXL (AXL receptor tyrosine kinase)
Diseases named in the same sentence as AXL in open-access papers (continued):
Sharing a sentence is not in itself a finding about the gene and the disease.
Cirrhosis (6 papers, 2020 to 2025). A chronic disorder of the liver in which liver tissue becomes scarred and is partially replaced by regenerative nodules and fibrotic tissue resulting in loss of liver function. "In cirrhosis, AXL expression on KCs was significantly reduced in association with disease severity and infectious complications." (PMID 37004869, 2023). "Next, we aimed to understand the underlying mechanisms as to how AXL expression on liver macrophages was reduced on the evolution of cirrhosis." (PMID 37004869, 2023). "AXL expression on macrophages was lost in the process of fibrosis progression and portal hypertension in cirrhosis and implicated infectious complications." (PMID 37004869, 2023). "We newly describe the expansion of an AXL-expressing immune-regulatory monocyte subset (CD14+HLA-DR+AXL+) along cirrhosis progression and its close association with disease severity, infection susceptibility, development of AD, and prognosis." (PMID 31822557, 2020). "We further revealed that AXL expression on monocytes in cirrhosis was associated with inhibition of T cell proliferation, when tested in an allogeneic mixed lymphocyte reaction." (PMID 31822557, 2020). "Immunotherapeutic modulation of AXL may represent an option deserving evaluation to augment immune responses and reduce infection susceptibility, morbidity, and mortality in cirrhosis." (PMID 31822557, 2020). "The role of AXL expression on tissue macrophages in the liver and associated compartments such as gut and peritoneum in the context of immune-homeostasis regulation in health and cirrhosis as a multisystem disorder remained unknown." (PMID 37004869, 2023). "Although translocated bacterial products as well as pathogen and apoptotic cell uptake lead to an increase of AXL expression on circulating monocytes in patients with advanced cirrhosis, it remained unknown which mechanisms underlie the down-regulation on macrophages." (PMID 37004869, 2023). "Given the distinct immune-regulatory functions of the AXL+ monocyte population in patients with cirrhosis and its association with disease severity and infection, we questioned whether inhibition or down-regulation of AXL would reverse the anti-inflammatory properties." (PMID 31822557, 2020). "AXL+ highly efferocytic mature monocytes are expanded in the peripheral blood of patients with cirrhosis, which is correlated with complications and poor outcomes." (PMID 40721870, 2025). "GAS6, secreted by activated hepatic stellate cells, decreased AXL on liver macrophages in relation to cirrhosis progression." (PMID 37004869, 2023). "Having observed AXL expression on most resident macrophages in healthy livers, we assessed AXL expression at different disease stages of cirrhosis." (PMID 37004869, 2023). "Stimulation with GAS6 significantly decreased AXL expression on primary liver macrophages isolated from either 2 patients with cirrhosis or a pathologic control (NCPH) ex vivo, and co-culturing with LX-2 cells displayed a trend for reduced AXL expression." (PMID 37004869, 2023). "We also studied AXL on KCs of patients with advanced cirrhosis who underwent transplantation and observed an increase of AXL expression after transplantation." (PMID 37004869, 2023). "In patients with cirrhosis, we also observed a reduced expression of AXL on gut and peritoneal macrophages, whereas AXL expression was elevated on macrophages in mesenteric lymph nodes." (PMID 37004869, 2023). "The role of AXL expression on gut macrophages in intestinal inflammation and cirrhosis is subject of ongoing studies." (PMID 37004869, 2023). "Inversely, we observed an increase of AXL+ macrophages along with cirrhosis regression (patients 4 and 5) or after liver transplantation (patients 3 and 6)." (PMID 37004869, 2023). "Previously we identified the emergence of circulating immune-modulatory monocytes expressing AXL in parallel with disease progression of cirrhosis that dampened immune responses to microbial challenge." (PMID 37004869, 2023).
Cirrhosis (continued). "Decreased AXL expression on resident liver macrophages in advanced cirrhosis, potentially in response to activated HSC-secreted GAS6, suggests a role for AXL in the regulation of hepatic immune homeostasis." (PMID 37004869, 2023). "We also performed immunofluorescent staining on liver biopsies and liver resection tissue from patients with cirrhosis and controls showing AXL, α-SMA, and GAS6 expression." (PMID 37004869, 2023). "In cirrhosis, we observed a significant decrease in AXL-expressing resident liver macrophages in parallel with disease severity." (PMID 37004869, 2023). "We found a decrease in AXL+ liver macrophages in parallel with progression of cirrhosis stage (patients 1–3)." (PMID 37004869, 2023). "We recently described the occurrence of AXL-expressing circulating monocytes in cirrhosis characterized by impaired inflammatory responses, thereby favoring immuneparesis, which were reversed by bemcentinib ex vivo." (PMID 37004869, 2023). "Ex vivo data obtained from patients at different stages of cirrhosis support the potential strategy of targeting TAM receptors AXL and MERTK." (PMID 36926073, 2022). "Immuneregulatory AXL-expressing monocytes expanded along with the progression of cirrhosis, representing <5% in early stages and up to 40% of monocytes in later stages, but were scarce following an event triggering AD (<5%)." (PMID 36926073, 2022). "In parallel with increased disease severity and the decline of inflammatory cytokine production in response to LPS, we demonstrated the expansion of an AXL-expressing monocyte population ex vivo in the circulation of patients with cirrhosis." (PMID 31822557, 2020). "In contrast to M-MDSCs, generated in vitro by culturing monocytes in ACLF plasma, inflammatory factors in plasma of patients with cirrhosis were necessary, but insufficient to induce AXL up-regulation alone." (PMID 31822557, 2020). "In conclusion, the number of AXL-expressing immune-regulatory monocytes in the circulation of patients with cirrhosis indicated disease severity, immuneparesis, infection susceptibility, AD, and mortality." (PMID 31822557, 2020). "Consistent with the observations in patients with cirrhosis ex vivo, AXL-expressing THP-1 cells produced less TNF-α and IL-6 in response to LPS when compared with non-transduced THP-1 cells." (PMID 31822557, 2020). "Metformin-induced down-regulation of AXL was confirmed in monocytes from patients with cirrhosis ex vivo here." (PMID 31822557, 2020). "To investigate the effect of the expanded CD14+HLA-DR+AXL+ subset on the impaired inflammatory cytokine responses observed in monocytes from patients with cirrhosis we assessed the functional properties of AXL+ monocytes ex vivo." (PMID 31822557, 2020). "Detailed analyses of the distinct subsets revealed that TNF-α/IL-6 production in response to LPS was decreased in both CD14+HLA-DR+AXL+ monocytes and M-MDSCs when compared with CD14+HLA-DR+AXL− monocytes from patients with cirrhosis and HC." (PMID 31822557, 2020). "Although CD14+HLA-DR+AXL+ cells accumulated with worsening stages of cirrhosis, they disappeared upon acute hepatic decompensation." (PMID 31822557, 2020). "This underlines the distinct and counter-regulatory roles of AXL and MERTK in different phases of cirrhosis and inflammation." (PMID 31822557, 2020). "Similarly, we observed low AXL but increased MERTK expression on peritoneal macrophages of decompensated cirrhosis patients with ascites." (PMID 37004869, 2023). "It remains unknown whether pMACs express AXL under physiological or disease conditions other than cirrhosis." (PMID 37004869, 2023). "Prevalence of hepatic CD68+AXL+ cells significantly decreased with cirrhosis progression: (healthy, 90.2%; Child-Pugh A, 76.1%; Child-Pugh B, 64.5%; and Child-Pugh C, 18.7%; all P < .05) and negatively correlated with Model for End-Stage Liver Disease and C-reactive protein (all P < .05)." (PMID 37004869, 2023).
Cirrhosis (continued). "This may imply first evidence that AXL inhibitors may be safely used and further evaluated in patients with cirrhosis." (PMID 37004869, 2023). "In summary, the reduction of AXL expression on liver macrophages on the evolution of cirrhosis presumably involves different mechanisms, potentially including GAS6-mediated down-regulation of AXL and migration of AXL-expressing monocytic cells to extrahepatic compartments." (PMID 37004869, 2023). "Hence, further studies are necessary to investigate the dynamics of AXL expression on KCs during cirrhosis evolution." (PMID 37004869, 2023). "Because of the accumulation of AXL-expressing cells in the circulation and lymph nodes in cirrhosis, we hypothesized these cells may have migratory properties." (PMID 37004869, 2023). "Here, we assessed AXL expression on tissue macrophages in patients with cirrhosis." (PMID 37004869, 2023). "Considering cirrhosis as a systemic disease condition, in this study we sought to assess the plasticity of AXL expression on tissue macrophages in different compartments of patients with advanced cirrhosis and to investigate its potential role in immune homeostasis regulation." (PMID 37004869, 2023). "Importantly, the CD14+HLA-DR+AXL+ immune cell subset detailed here has to be distinguished from the recently identified immunosuppressive M-MDSCs in patients with cirrhosis and ACLF, which we observed expanding from Child A to C in our cohort." (PMID 31822557, 2020). "AXL may thus serve as prognostic marker and deserves evaluation as immunotherapeutic target in cirrhosis." (PMID 31822557, 2020). "Based on our findings, the number of AXL-expressing monocytes in blood count may represent a prognostic biomarker for immuneparesis and cirrhosis and validates further evaluation." (PMID 31822557, 2020). "We propose that in cirrhosis, AXL may be operative in settings where the nature of injury is driven by excessive pro-inflammatory responses, as present in diverse underlying aetiologies." (PMID 31822557, 2020). "Extensive characterisation of the AXL-expressing monocyte population revealed an immune-regulatory subset that emerged in the circulation likely to maintain immune homoeostasis despite rising inflammatory signals during progression of cirrhosis." (PMID 31822557, 2020). "As a mechanism, we showed previously that AXL expression on monocytes was enhanced in response to microbial products and efferocytosis, which may explain their abundance in the circulation in the context of cirrhosis." (PMID 37004869, 2023). "At certain stages of cirrhosis, the effect of AXL inhibition might be desirable in the systemic circulation but not necessarily in the liver, gut, and presumably other tissues because liver and gut macrophages revealed reduced AXL expression in advanced cirrhosis." (PMID 37004869, 2023). "Thus, we hypothesized that GAS6 released by aHSCs in the context of cirrhosis may lead to AXL down-regulation in resident liver macrophages." (PMID 37004869, 2023). "Because of the enhanced migratory potential of AXL-expressing monocytic cells and their enhancement in other compartments in the condition of advanced cirrhosis, it is conceivable that AXL-expressing cells may egress the liver and migrate towards regional lymph nodes and/or the systemic circulation." (PMID 37004869, 2023). "Therefore, the flow cytometry-based analysis of AXL expression on monocytes in patients with cirrhosis might serve as a marker of immuneparesis and identify patients at risk for infection and deterioration." (PMID 36926073, 2022). "The CD14+HLA-DR+AXL− population represented the majority of monocytes in HC, indicating it may be regarded “functionally intact” but was sequentially lost in the circulation of patients with progression of cirrhosis." (PMID 31822557, 2020).
Cirrhosis (continued). "The stimulatory effect of pathogen uptake on AXL expression is novel and may explain high AXL expression on circulating monocytes in conditions where pathogens and their products become abundant because of pathologic bacterial translocation such as cirrhosis." (PMID 31822557, 2020). "AXL and MERTK expression on circulating monocytes modulated immune responses in patients with cirrhosis (CD14+HLA-DR+AXL+) and acute-on-chronic liver failure (CD14+MERTK+)." (PMID 37004869, 2023). "In compensated cirrhosis and NAD, the expansion of AXL-expressing circulating monocytes correlated with the occurrence of infectious episodes, onset of subsequent AD within 4 months and 1-year mortality." (PMID 36926073, 2022). "As an inexpensive, well-established drug, metformin may represent an interesting immunomodulatory treatment option for patients with cirrhosis and no signs of AD, when AXL-expressing monocytes are frequent and the risk for metformin-associated lactic acidosis is low." (PMID 31822557, 2020). "Given the distinct and reciprocal expression profiles of AXL and MERTK in cirrhosis, it further needs to be addressed which receptor to target at which stage of disease and in which compartment." (PMID 31822557, 2020). "Nevertheless, liver macrophages in cirrhosis patients presented reduced phagocytosis capacity of Gram-negative bacteria unrelated to AXL." (PMID 37004869, 2023). "Using multiplexed immunofluorescence we compared AXL expression in liver biopsies in cirrhosis (n = 22), chronic liver disease (n = 8), non-cirrhotic portal hypertension (n = 4), and healthy controls (n = 4)." (PMID 37004869, 2023). "AXL expressing immune-regulatory monocytes have been shown to increase in patients during progression of cirrhosis independent of the aetiology and prior to AD and related infectious complications, as well as the future onset of AD and mortality." (PMID 36926073, 2022). "AXL+ monocytes showed preserved phagocytosis capacities for E. coli bioparticles and live E. coli bacteria, whereas M-MDSCs revealed reduced phagocytosis, when compared with CD14+HLA-DR+AXL− monocytes from patients with cirrhosis and HC." (PMID 31822557, 2020). "When comparing AXL+ with AXL− monocyte populations from patients with cirrhosis following metformin treatment, cytokine production was enhanced in AXL+ but not AXL− cells." (PMID 31822557, 2020). "AXL expression on monocytes of patients with CLD without cirrhosis was low; a similar pattern was also seen in AD." (PMID 31822557, 2020). "Our data do not support the assumption that in cirrhosis AXL+ macrophages may be transformed towards MERTK+ macrophages, because we did not see that loss of AXL would lead to an up-regulation of MERTK on primary human macrophages ex vivo (data not shown)." (PMID 37004869, 2023). "From one patient with advanced cirrhosis (Child-Pugh C) who underwent transplantation, we investigated macrophages in mesenteric lymph nodes and observed the presence of CD68+AXL+ macrophages accumulating in the non-follicular regions." (PMID 37004869, 2023).
esophageal adenocarcinoma (6 papers, 2016 to 2025). A malignant tumor with glandular differentiation arising predominantly from Barrett mucosa in the lower third of the esophagus. "AXL receptor tyrosine kinase promotes an invasive phenotype and chemotherapy resistance in esophageal adenocarcinoma (EAC)." (PMID 35936716, 2022). "Noteworthy, AXL has been shown recently to mediate the anterograde trafficking of lysosomes (Lamp1-positive vesicles) in esophageal adenocarcinoma cells, regulating the secretion of cathepsin B, which is involved in matrix degradation and invasion." (PMID 31963783, 2020). "AXL has been reported as an adverse prognostic factor and a therapeutic target in esophageal adenocarcinoma (EAC)." (PMID 27172793, 2016). "AXL receptor tyrosine kinase is overexpressed in esophageal adenocarcinoma (EAC) and several other types of malignancies; hence, it may be a valuable therapeutic target." (PMID 30353671, 2018). "AXL is ubiquitously expressed in cells and organs, and its over-expression has been reported in a wide array of human cancers, including breast, lung, liver, colon, and esophageal adenocarcinoma." (PMID 27172793, 2016). "However, the functional and molecular signaling relationship between AXL and c-ABL, and the clinical significance of their expression in esophageal adenocarcinoma remain not fully investigated." (PMID 32922529, 2020).
esophageal squamous cell carcinoma (6 papers, 2016 to 2023). Esophageal squamous cell carcinoma (ESCC) is a type of esophageal carcinoma (EC) that can affect any part of the esophagus, but is usually located in the upper or middle third. "AXL expression is linked to adverse prognosis in EAC as well as poor prognosis and distant metastases in esophageal squamous cell carcinoma." (PMID 37469409, 2023). "A growing body of evidence suggests that AXL is closely associated with EMT, and can be used as an EMT marker in several types of cancer, including esophageal squamous cell carcinoma (ESCC)." (PMID 37328828, 2023). "It is tempting to speculate that PROS1-driven AXL expression may lead to functional receptor heterodimerization with EGFR, as was shown for HNSCC and esophageal squamous cell carcinoma." (PMID 28118606, 2017).
heart failure (6 papers, 2016 to 2025). Inability of the heart to pump blood at an adequate rate to meet tissue metabolic requirements. "The significance of the Gas6/AXL complex in heart failure warrants further investigation." (PMID 40933570, 2025). "Other label-free electrochemical immunosensors have been reported for the determination of myoglobin (cMyo), parathion, and the receptor tyrosine kinase AXL, a relevant biomarker in cancer, inflammatory processes, and heart failure, at screen-printed carbon electrodes (SPCEs) modified with GQDs." (PMID 31010125, 2019). "Interestingly, there was an association of sAXL at seven days post MI with left ventricular remodeling, indicative of an activation of AXL signaling or its processing in the initial stages of heart failure in connection with cardiac structural changes in the initial stages of heart failure." (PMID 36983628, 2023). "In addition, the immunosensor for parathion could be re-used during five regeneration cycles and the immunosensors for AXL and cMyo were successfully applied to the determination of the cardiac biomarkers in spiked human serum and in serum from heart failure (HF) patients." (PMID 31010125, 2019). "A study using a rat model reported that AXL level increases in the early stages of left ventricular remodelling with pressure overload, with no further increase in heart failure." (PMID 39992996, 2025).